S100A11 (S100 calcium binding protein A11)
Diseases named in the same sentence as S100A11 in open-access papers (continued):
Sharing a sentence is not in itself a finding about the gene and the disease.
pterygium (2 papers, 2009 to 2022). A wedge-shaped fibrovascular lesion arising from the bulbar conjunctiva and extending to the cornea. "S100A4, S100A6, S100A8, S100A9, and S100A11 gene transcripts were detected in conjunctiva and pterygium tissues." (PMID 19223989, 2009). "S100A11 was expressed in the basal cells of conjunctival epithelium but in the suprabasal layers of pterygium epithelium." (PMID 19223989, 2009). "A similar pattern of alteration in the localization of S100A11 was seen in our study, which further suggests that pterygium is related to an anomaly in epithelial differentiation." (PMID 19223989, 2009). "A distinctly different expression pattern of S100A11 was noted in pterygium epithelium when compared to the uninvolved conjunctiva." (PMID 19223989, 2009). "We found the presence of S100A11 in the plasma membrane of uninvolved human conjunctiva and pterygium epithelial cells." (PMID 19223989, 2009). "Our investigation revealed that S100A4, S100A6, S100A8, S100A9, and S100A11 are expressed in both the normal and pterygium epithelia." (PMID 19223989, 2009). "Western blot and RT–PCR confirmed the presence of S100A4, S100A6, S100A8, S100A9, and S100A11 in pterygium and conjunctiva tissue." (PMID 19223989, 2009). "Immunofluorescent staining detected the presence of S100A4, S100A6, S100A8, S100A9, and S100A11 in normal human conjunctival and pterygium epithelia." (PMID 19223989, 2009). "In addition, a distinct alteration of localization of S100A11 expression was observed in pterygium epithelium compared to the conjunctiva." (PMID 19223989, 2009). "Protein levels of S100A4 and S100A11 in the pterygium tissue was not significantly different compared with the normal conjunctiva." (PMID 19223989, 2009). "Similar to the protein expression, S100A4 and S100A11 did not demonstrate any significant difference in expression in either pterygium or conjunctival tissues." (PMID 19223989, 2009).
small cell lung carcinoma (2 papers, 2016 to 2023). Small cell lung cancer (SCLC) is a highly aggressive malignant neoplasm, accounting for 10-15% of lung cancer cases, characterized byrapid growth, and early metastasis. "S100A11 was overexpressed in small cell lung cancer and suggested the poor survival." (PMID 36605485, 2023). "As an example, S100A11 expression is increased in NSCLC, but is decreased in small-cell lung cancer." (PMID 27709523, 2016).
type 2 diabetes (2 papers, 2020 to 2022). "Using pharmacophore target analysis in a network pharmacology approach, we identified five potential target genes for celastrol in the treatment of type 2 diabetes, including RBP3, BMP7, S100A11, HBB and IQUB." (PMID 36339449, 2022).
alcohol dependence (1 paper, 2020). Physical and psychological dependence on alcohol. "The study implies that inflammation associated with the development of alcohol dependence might be partially mediated by S100A11 and SERPINC1 proteins." (PMID 32778093, 2020). "For instance, we were able to link S100A11 and SERPINC1, proteins associated with pQTLs in hotspots 17 and 18, to alcohol dependence through their distant pQTL variants located in ADH1C." (PMID 32778093, 2020). "Our results suggest that S100A11 and SERPINC1 may be involved in molecular mechanisms underlying the association between rs698 and alcohol dependence." (PMID 32778093, 2020).
benign ovarian tumor (1 paper, 2021). "Serum levels of S100A11 and MMP9 were detected in patients with EOC, patients with benign ovarian tumor, and healthy women." (PMID 33763485, 2021). "The serum levels of S100A11 and MMP-9 in patients with EOC were higher than those in patients with benign ovarian tumor and in healthy women, and the expression levels of S100A11 and MMP-9 were positively correlated." (PMID 33763485, 2021).
bladder tumors (1 paper, 2012). "In bladder tumors, overexpression of S100A4, S100A8 or S100A11, but not S100A9 in cancer tissues is associated with stage progression, invasion, metastasis and poor survival." (PMID 22838504, 2012).
breast tumors (1 paper, 2012). "Additionally, S100A11 was shown to change from a strictly nuclear localization in normal breast tissue to a more cytoplasmic localization in breast tumors." (PMID 22727333, 2012).
calcification (1 paper, 2025). Process by which organic tissue becomes hardened by the physiologic deposit of calcium salts. "S100A11 is a member of the S100 family that mediates signaling in response to internal or external stimuli and plays a variety of roles in diseases as diverse as cancer, metabolic diseases, neurological disorders, and vascular calcification." (PMID 39854580, 2025).
Cerebral ischemia (1 paper, 2018). Restriction of arterial blood supply to the brain associated with insufficient oxygenation to support the metabolic requirements of the tissue. "Based on our findings, treatments that increase the interaction between S100A11 with ANXA1 may represent a promising therapeutic strategy for cerebral ischemia." (PMID 29844306, 2018).
Cirrhosis (1 paper, 2009). A chronic disorder of the liver in which liver tissue becomes scarred and is partially replaced by regenerative nodules and fibrotic tissue resulting in loss of liver function. "In the present study, the expression level of S100a10, S100a11, S100a6, S100a8 and S100a9 increased from cirrhosis to metastatic process when compared with the normal liver." (PMID 19638242, 2009).
clear cell sarcoma (1 paper, 2023). A rare malignant neoplasm with melanocytic differentiation characterized by the presence of polygonal or spindle shaped clear cells. "The S100A11 gene was found to be significantly upregulated in clear cell sarcoma of soft tissue." (PMID 36988561, 2023).
colitis (1 paper, 2022). Inflammation of the colon. "ScRNA-seq analysis of colon and colitis showed that embryonic-specific genes reappear in response to intestinal damage, which is conserved both in human IBD and mouse DSS-induced colitis, including MYO15B, S100A11, and CDV3." (PMID 36045190, 2022).
colorectal adenocarcinoma (1 paper, 2019). The most common type of colorectal carcinoma. "In keeping with these findings, expression of annexin A1 strongly correlated with S100-A11 expression in the Tissue Cancer Genome Atlas data set of colorectal adenocarcinoma patients, both at mRNA and protein levels." (PMID 31545917, 2019).
diabetic retinopathy (1 paper, 2025). "Although S100A11 was identified in tears of subjects with ocular diseases such as dry eye and meibomian gland disfunction, our work showed the abundance levels of S100A11 in tears was altered in preDM and T2DM subjects even before the appearance of symptoms and signs of diabetic retinopathy." (PMID 40700273, 2025).
head and neck carcinoma (1 paper, 2023). A carcinoma that arises from the head and neck region. "For instance, S100A11 knockdown causes a decrease in phosphorylated PI3K, phosphorylated Akt, and phosphorylated mTOR and disturbs cell proliferation and migration in head and neck carcinoma cells, indicating that the upregulation of S100A11 activates the PI3K–Akt-mTOR pathway in these tumor cells." (PMID 36835331, 2023).
Hypertension (1 paper, 2020). The presence of chronic increased pressure in the systemic arterial system. "Some of the modulated proteins in saliva such as HSPA8 or S100A9 have been previously related to DM complications such as hypertension or micro-vascular alterations, while others such as S100A2 and S100A11 are described in DM here for the first time." (PMID 33271797, 2020).
ileitis (1 paper, 2021). "In this regard, host alarmins S100A11 and IL-33 have been implicated in monocyte recruitment and aggravated ileitis respectively during T. gondii infection, although their role in IL-12-driven immunity is not clear." (PMID 34597344, 2021).
inflammatory bowel disease (1 paper, 2018). A spectrum of small and large bowel inflammatory diseases of unknown etiology. "Along with those already mentioned, other top up-regulated DEGs such as Uck2, Krt23, Pcsk9, and S100a11 have also been associated with cancer or inflammatory bowel disease (IBD), likely reflecting their roles in cell proliferation or repair." (PMID 29339782, 2018).
Insulin resistance (1 paper, 2023). Increased resistance towards insulin, that is, diminished effectiveness of insulin in reducing blood glucose levels. "These liver-specific data further suggest that S100A11 may play a role in the pathogenesis of impaired glucose metabolism and insulin resistance." (PMID 36872321, 2023). "Moreover, in the male population, S100A11 levels could predict β-cell function after adjusting for insulin resistance and considering the degree of insulin sensitivity." (PMID 36872321, 2023). "Furthermore, S100A11 was nonlinearly correlated with FPG, FPI, HOMA-IR, hepatic ISI, WBISI, and CIR in patients with IGT and DM, suggesting that S100A11 is involved in insulin resistance, pancreatic β-cell function, and hepatic and whole-body insulin sensitivity." (PMID 36872321, 2023).
laryngeal carcinoma (1 paper, 2014). Carcinoma that arises from the laryngeal epithelium. "Considerable proteins, such as YWHAZ, S100-A11, glutathione S-transferase, alpha-enolase, flavin reductase, fascin, and carbonic anhydrase, have been reported to be associated with laryngeal carcinoma in previous proteomics studies but without clinical validation and in-depth functional research." (PMID 24587265, 2014).
liver cirrhosis (1 paper, 2023). "So, we are unable to determine if S100A11 can distinguish between patients with liver cirrhosis and those with HCC." (PMID 36860671, 2023).
lymphoma (1 paper, 2022). A malignant (clonal) proliferation of B- lymphocytes or T- lymphocytes which involves the lymph nodes, bone marrow and/or extranodal sites. "For example, before the lymphoma phenotype was evident in the preleukemic stage, one of the earliest genes to be upregulated was s100a11 (top), which overexpression has been reported to promote cell proliferation, antiapoptotic, and tumor metastasis in various cancers." (PMID 35504924, 2022).
meningioma (1 paper, 2023). A generally slow growing tumor attached to the dura mater. "The analysis showed that a combination of MUC4 and MUC1 followed by SPTB2 and S100A11 showed segregation as a marker pair between low grade and high grade meningioma in tissue." (PMID 37770851, 2023). "Using these diagnostic markers like MUC1, S100A11, and ANXA1, this approach could be tested out as an alternative to confirm the early prognosis of Meningioma." (PMID 37770851, 2023). "In this study, S100A11 was found to be significantly upregulated in high grade meningioma." (PMID 37770851, 2023).
metastatic cancer (1 paper, 2022). A carcinoma which has spread from the original site of growth to another anatomic site. "S100A11 has also been shown to associate with ANXA2 and this interaction is required for efficient PM wound repair and subsequent survival of metastatic cancer cells." (PMID 36200035, 2022).
Myocardial fibrosis (1 paper, 2021). "Overall, Tranilast inhibits angiotensin II-induced myocardial fibrosis through S100A11/TGF-β1/Smad axis." (PMID 34663163, 2021). "In conclusion, our paper confirmed that Tranilast inhibited Ang II-induced myocardial fibrosis through S100A11/TGF-β1/ Smad axis." (PMID 34663163, 2021). "Therefore, we concluded that Tranilast inhibited Ang II-induced myocardial fibrosis by down-regulating S100A11." (PMID 34663163, 2021). "Therefore, we hypothesized that Tranilast could inhibit Ang II-induced myocardial fibrosis by down-regulating S100A11/TGF-β1/Smad axis." (PMID 34663163, 2021).
myositis (1 paper, 2023). "In addition, S100A11 was correlated with the levels of lactate, a marker of inflammation, in patients with myositis." (PMID 37510130, 2023).
neuroblastoma (1 paper, 2025). Neuroblastoma (NB) is the most common solid, extracranial childhood tumor. "To confirm their transcriptional activity, we used a Neuro 2A, a mouse neuroblastoma cell line, to perform luciferase assay using the promoters of S100A6 and S100A11." (PMID 40882002, 2025).
oral squamous cell carcinomas (1 paper, 2020). "S100A2 in saliva has been proposed as a candidate biomarker for the early detection of oral squamous cell carcinomas in humans and S100A11 is overexpressed in several human cancers tissues, although to the author’s knowledge there are no reports that evaluate these two proteins in DM in humans." (PMID 33271797, 2020).
pancreatitis (1 paper, 2025). Inflammation of the pancreas. "Third, given the complex mechanisms underlying pancreatitis, additional molecular studies are needed to explore whether S100A11 directly interacts with genes involved in ferroptosis and to elucidate the specific mechanisms through which this interaction occurs." (PMID 40538500, 2025).
papillary thyroid carcinoma (1 paper, 2015). "Overexpression of S100A11 has been reported in a number of cancers, including papillary thyroid carcinoma, colon, pancreatic and breast cancer." (PMID 25780452, 2015). "In addition, silencing S100A11 expression has been shown to reduce the anchorage-independent growth of papillary thyroid carcinoma cells." (PMID 25780452, 2015).
Pleural effusion (1 paper, 2018). The presence of an excessive amount of fluid in the pleural cavity. "We found that the secretion of S100A11 was significantly higher in MPM pleural effusions, compared to others, suggesting the possibility for the use of S100A11 as a biomarker." (PMID 29362358, 2018). "To explore the possibility of using S100A11 as a useful marker for diagnosis of MPM, we examined the secretion levels of S100A11 in several types of pleural effusions." (PMID 29362358, 2018). "The concentration of S100A11 in MPM pleural effusions was significantly higher than that in pleural effusions of BA and postoperative patients, though the amount of secreted S100A11 is high in pleural effusions from both patients with MPM and BA." (PMID 29362358, 2018). "The level of S100A11 was remarkably elevated in pleural effusion obtained from MPM patients when compared to that obtained from BA patients as a benchmark (P = 0.014)." (PMID 29362358, 2018). "We hence examined the secretion level of S100A11 in pleural effusion." (PMID 29362358, 2018). "In addition, it is of note mentioning that the concentration of S100A11 in the pleural effusions of patients with BA was significantly higher than that of postoperative patients." (PMID 29362358, 2018). "Taking it into account, we consider that MPM cells actively secrete S100A11 in pleural effusion." (PMID 29362358, 2018). "Furthermore, we found that the secretion level of S100A11 was significantly higher in pleural effusion from BA patients than that from postoperative patients (P = 0.041)." (PMID 29362358, 2018). "In addition, we examined the secretion level of S100A11 in various types of pleural effusions." (PMID 29362358, 2018).
prediabetes (1 paper, 2023). "Therefore, S100A11 can be used to diagnose prediabetes, and S100A11 combined with HbA1c can monitor long-term glycemic control." (PMID 36872321, 2023).
pulmonary arterial hypertension (1 paper, 2021). Pulmonary arterial hypertension (PAH) is a group of diseases characterized by mean pulmonary artery pressure >20 mmHg and elevated pulmonary arterial resistance leading to right heart failure. "S100A11 levels are increased in the plasma of patients with pulmonary arterial hypertension (PAH)." (PMID 34239729, 2021).
sarcoma (1 paper, 2023). A usually aggressive malignant neoplasm of the soft tissue or bone. "In sarcoma, the expression levels of ANXA1 were positively correlated with those of MMP9 (r=0.204, P=9.43e-04), COL1A2 (r=0.349, p=8.87e-09), S100A4 (r=0.574, P<0.001), VIM (r=0.48, P<0.001) and S100A11 (r=0.638, P<0.001)." (PMID 36988561, 2023).
schistosomiasis (1 paper, 2024). An infectious disease caused by parasitic trematodes of the genus Schistosoma that colonize human blood vessels and release eggs that can cause granulomatous reactions leading to acute (swimmer's itch or acute schistosomiasis syndrome) or chronic disease. "Although the roles of S100A8 and S100A11 have not yet been elucidated in schistosomiasis, the S100A proteins are known as effector molecules that can block the development of several invading pathogens such as Salmonella typhimurium and Staphylococcus aureus." (PMID 39398025, 2024).
Stroke (1 paper, 2018). Sudden impairment of blood flow to a part of the brain due to occlusion or rupture of an artery to the brain. "Thus, S100A11 overexpression significantly improves neuronal survival, protects against stroke damage, and even improves spatial learning and memory and motor function." (PMID 29844306, 2018). "Therefore, whether the impressive efficacy of S100A11 overexpression would probably translate to human stroke still remained to be discussed in further research work." (PMID 29844306, 2018).
Venous malformation (1 paper, 2023). A vascular malformation resulting from a developmental error of venous tissue composed of dysmorphic channels lined by flattened endothelium and exhibiting slow turnover. "The expression of LEF1-AS1 was upregulated in venous malformations, and the expression of S100A11 was increased by the adsorption of miR-489-3p to venous endothelial cells, thus enhancing the proliferation, migration, and angiogenesis of HUVEC cells." (PMID 37927791, 2023). "In conclusion, LEF1-AS1 is involved in the occurrence and development of venous malformations by regulating the miR-489-3p/S100A11 axis, which provides valuable insights into the pathogenesis of this disease and opens new avenues for its treatment." (PMID 37927791, 2023). "This study aimed to elucidate the role of the lncRNA LEF1-AS1 in the development of venous malformations and examine the interaction among LEF1-AS1, miR-489-3p, and S100A11 in HUVEC cells." (PMID 37927791, 2023). "The findings of tissue experiments revealed that the expressions of LEF1-AS1 and S100A11 were higher in tissues with venous malformations than in normal tissues, whereas the expression of miR-489-3p was lower in venous malformations than in normal tissues." (PMID 37927791, 2023).